APOA2 (apolipoprotein A2)
Diseases named in the same sentence as APOA2 in open-access papers (continued):
Sharing a sentence is not in itself a finding about the gene and the disease.
colon adenocarcinoma (1 paper, 2024). "APOA2 is known to be involved in high density lipoprotein (HDL) metabolism, while acyl-CoA thioesterase 7 (ACOT7) is important in unsaturated fatty acid biosynthesis which is involved in the initiation and progression of colon adenocarcinoma (COAD)." (PMID 39494346, 2024).
coronary artery spasm (1 paper, 2021). "Among these DEPs, the protein encoded by the APOA2 transgene affects the development of atherosclerotic lesions in a mouse model, and the SGCG protein decreases coronary artery spasm in mice." (PMID 34418970, 2021).
depression (1 paper, 2023). "APOA2 is related to tryptophan metabolism, which is not only related to appetite but also to depression, as tryptophan is the main precursor of serotonin." (PMID 37296094, 2023).
endothelial dysfunction (1 paper, 2018). In vascular diseases, endothelial dysfunction is a systemic pathological state of the endothelium (the inner lining of blood vessels) and can be broadly defined as an imbalance between vasodilating and vasoconstricting substances produced by (or acting on) the endothelium. "In our study, among differentially expressed proteins were PLG, SERPING1, SERPINC1, APOA2, FGB, A2M, which are related to endothelial dysfunction, coagulation processes and pro-atherogenic alteration mechanisms." (PMID 29755368, 2018).
Hernia (1 paper, 2018). "Apolipoproteins were analyzed with an immunoassay for multiplexed detection of APOA1, APOA2, APOB, APOC2, APOC3, and APOE, and all six proteins were found to be significantly elevated in urine samples of BC patients when compared to controls (hernia patient volunteers)." (PMID 30544619, 2018).
hypersensitivity pneumonitis (1 paper, 2017). Hypersensitivity pneumonitis (HP) is a pulmonary disease with symptoms of dyspnea and cough resulting from the inhalation of an antigen to which the subject has been previously sensitized. "HBB and APOA2 could help discriminate between IPF and healthy controls, but was unable to be applied for differential diagnostic of IPF and sarcoidosis, and IPF and hypersensitivity pneumonitis, respectively." (PMID 28122020, 2017). "No statistical difference was recorded on the concentrations of CRP and APOA2 among the IPF, sarcoidosis and hypersensitivity pneumonitis groups." (PMID 28122020, 2017).
liposarcoma (1 paper, 2005). A usually painless malignant tumor that arises from adipose tissue. "In this study, we did FISH with a contig of BACs spanning 7 Mb around APOA2 to map and characterize this amplicon in more detail in liposarcoma LS21, which showed the highest copy number of APOA2 in previous analyses." (PMID 16274472, 2005).
liver cirrhosis (1 paper, 2020). "Recently, there has been a comprehensive report on circulating mRNA analysis, and among the mRNAs whose expression is different between HCC and liver cirrhosis and the mRNA in liver tissue used for this analysis, Alb, ApoA1, ApoA2, and Ftl was common with both study." (PMID 33303811, 2020).
lung diseases (1 paper, 2017). "A set of three most significantly upregulated proteins (HBB, CRP and SERPINA1) and four most significantly downregulated proteins (APOA2, AHSG, KNG1 and AMBP) were selected for validation in an independent cohort of IPF and other lung diseases using ELISA test." (PMID 28122020, 2017).
Pancreatic cysts (1 paper, 2024). A cyst of the pancreas that possess a lining of mucous epithelium. "ApoA2-ATQ/AT has the potential for risk stratification of pancreatic cancer in screening a population with NOD, pancreatic cysts, and IPMN." (PMID 38261000, 2024).
psoriasis (1 paper, 2025). An autoimmune condition characterized by red, well-delineated plaques with silvery scales that are usually on the extensor surfaces and scalp. "In conclusion, our study highlights significant differences in serum apolipoproteins between patients with severe and mild psoriasis, with disease severity correlating negatively with the ApoA1/ApoA2 ratio." (PMID 40137160, 2025). "The aim of this study was to evaluate the potential associations between serum concentrations of apolipoproteins (ApoA1, ApoA2, ApoB, ApoC1, ApoC3, ApoD, ApoE, ApoH, and ApoJ) and various clinical and biochemical markers in patients with psoriasis." (PMID 40137160, 2025). "While limited prior research has primarily focused on apolipoproteins such as ApoA1, ApoA2, ApoB, ApoC1, ApoC3, and ApoE in psoriasis, our study uniquely extends this scope by also evaluating ApoD, ApoH, and ApoJ in this patient population for the first time." (PMID 40137160, 2025). "Further research is needed to confirm the potential of ApoA2 or ApoA1/ApoA2 ratio as a biomarker for metabolic dysregulation in psoriasis patients." (PMID 40137160, 2025). "While ApoA1 and ApoB in psoriasis have been the primary focus of research due to their established roles in lipid metabolism and cardiovascular risk, other apolipoproteins, such as ApoA2, ApoC1, ApoC3, ApoD, ApoE, ApoH, and ApoJ, have not been widely studied in psoriasis." (PMID 40137160, 2025). "We also observed a negative association between the Psoriasis Area and Severity Index (PASI) and ApoA1/ApoA2 ratio in the patients before the treatment." (PMID 40137160, 2025).
salivary gland tumors (1 paper, 2024). "Some of the identified peptides were derived from proteins previously suggested as potential biomarkers of salivary gland tumors (ANXA1, BPIFA2, FGB, GAPDH, HSPB1, IGHG1, VIM) or tumors of other tissues or organs (SERPINA1, APOA2, CSTB, GSTP1, S100A8, S100A9, TPI1)." (PMID 39201484, 2024).
sarcoma (1 paper, 2005). A usually aggressive malignant neoplasm of the soft tissue or bone. "Previous analyses of sarcomas have indicated the presence of at least two separate amplicons within this region, one located in 1q21 and one located near the apolipoprotein A-II (APOA2) gene in 1q23." (PMID 16274472, 2005).
seminoma (1 paper, 2015). A radiosensitive malignant germ cell tumor found in the testis (especially undescended), and extragonadal sites (anterior mediastinum and pineal gland). "For seminoma, this included LZTS1; for EC, DNMT3B, GAL and GPC4; for CHC CGA; and for YSTs AFP, APOA2, BMP2, VTN and OTX2." (PMID 25303610, 2015).
septic shock (1 paper, 2025). Shock caused by infection; frequently caused by gram negative bacteria, although some cases have been caused by other bacteria, viruses, fungi, and protozoa; characterized by fever, chills, tachycardia, tachypnea, and hypotension. "Patients with GG genotype of a tag SNP within the corresponding ApoA2 gene, rs6413453 G/A, had significantly higher 28-day mortality in two septic shock cohorts of different ancestry." (PMID 39980010, 2025).
Shock (1 paper, 2025). The state in which profound and widespread reduction of effective tissue perfusion leads first to reversible, and then if prolonged, to irreversible cellular injury. "In septic shock, apolipoprotein A-II levels and ApoA2 genetic variations are important factors associated with outcome." (PMID 39980010, 2025).
steatosis (1 paper, 2023). Increased lipid within the cytoplasm of cells. "The heatmap showed that the B4 cluster expressed a series of lipid-metabolism-associated genes, such as APOA1, APOA2, and APOA3, and UMAP plotting also showed that B4 cells highly expressed APOC1 and APOE, implying that the B4 cluster may be associated with steatosis in the ALC group." (PMID 36817578, 2023).
vasculitis (1 paper, 2022). "ApoA2 may be associated with a similar risk in mouse vasculitis models because it is one of the target antigens of VasSF, which has been developed as a novel antibody drug, derived from IgG, for vasculitis in SCG/Kj mouse." (PMID 36550471, 2022). "SCG/Kj mice which were administered anti-apolipoprotein A-2 antibodies (anti-ApoA2) recovered from vasculitis related renal disorders and showed a decrease in the levels of MPO-ANCA and inflammatory cytokines." (PMID 36550471, 2022). "The present study used a mouse model of CAWS-induced vasculitis to demonstrate that anti-ApoA2 shows potential as an effective therapeutic candidate for the treatment of KD vasculitis." (PMID 36550471, 2022). "Our results suggest that ApoA2, which is involved in vasculitis and is the second most abundant protein in high-density lipoprotein (HDL), stabilizes the structure of HDL via its association with lipids." (PMID 36550471, 2022). "In the present study, we examined the suppressive effect of anti-ApoA2 on the development of vasculitis with coronary arteritis in a CAWS-induced murine KD model via histological evaluation and the detection of inflammatory cytokines." (PMID 36550471, 2022). "Histological observations indicated that anti-ApoA2 induced histological changes in CAWS-induced vasculitis in a dose-dependent manner." (PMID 36550471, 2022). "The incidence and histological severity of vasculitis in CAWS-induced coronary arteritis in mice administered anti-ApoA2 was examined." (PMID 36550471, 2022). "The use of specific antibodies that display higher vasculitis-suppressing effects, such as anti-ApoA2, may attenuate KD as well as other infectious diseases, with less severe adverse side effects than treatment with IVIg." (PMID 36550471, 2022). "Our histological evaluation of vascular lesions and the measurement of serum cytokine/chemokine levels in the mouse KD model revealed that anti-ApoA2 treatment suppressed the development of coronary arteritis in a mouse model of KD vasculitis in a dose-dependent manner." (PMID 36550471, 2022). "On the other hand, panvasculitis in the aortic roots could not be completely suppressed even in the group administered with anti-ApoA2 0.1 mg/kg/day and hIgG, but the extent of vasculitis was smaller than that in the solvent group." (PMID 36550471, 2022). "This molecular interaction may suppress the decrease in anti-inflammatory activity, suggesting that anti-ApoA2 may be therapeutically effective not only in vasculitis, but also in various other diseases, such as cardiovascular and infectious diseases." (PMID 36550471, 2022). "The anti-ApoA2 treatment suppressed the development of coronary arteritis in an animal KD model and anti-ApoA2 shows potential as an effective therapeutic candidate for the treatment of KD vasculitis." (PMID 36550471, 2022). "Furthermore, anti-ApoA2 shows potential not only as a therapeutic agent but also as a tool that may be useful for elucidating the etiology and pathophysiology of KD and vasculitis." (PMID 36550471, 2022).
Ventricular hypertrophy (1 paper, 2022). Enlargement of the cardiac ventricular muscle tissue with increase in the width of the wall of the ventricle and loss of elasticity. "However, many mice in the anti-ApoA2 treatment group showed ventricular hypertrophy on both the sides than those in the hIgG treatment group, indicating that this may be one of the side effects of anti-ApoA2 treatment." (PMID 36550471, 2022).
tumor (36 papers, 2005 to 2026). "Integration of metabolomic and transcriptomic data revealed associations between APOA2 silencing, altered serum metabolite profiles, and enhanced macrophage activation, establishing a metabolic-immune-epigenetic cascade that promotes tumor fibrogenesis and progression." (PMID 42227003, 2026). "The APOA2+ neutrophils were enriched for metabolic pathways such as triglyceride metabolism and regulation of steroid metabolism and thus termed hepatic lipid-associated TANs and hepatic lipid-associated neutrophils or LANs, in the tumour and adjacent liver, respectively." (PMID 37534829, 2023). "APOA2 demonstrated differential expression between normal and tumor tissues, with its downregulation strongly correlated with promoter methylation (Spearman ρ = -0.31, P = 9.11 × 10-10)." (PMID 42227003, 2026). "The APOA2-i Index was approved as a tumor marker for PC in Japan in March 2024 and is now utilized clinically; however, there is a lack of studies evaluating its effectiveness in clinical practice." (PMID 40227633, 2025). "For chromatin accessibility data of scCPA‐Tag, the cluster exhibiting high gene activity scores for ALB, TTR, and APOA2 was identified as tumour cell." (PMID 39210544, 2024). "The screening model, integrating ApoA1, ApoA2, lithocholic acid (LCA), and CEA, attained an impressive AUC of 0.995, surpassing the diagnostic accuracy of individual lipids, bile acids, and tumor markers." (PMID 38698075, 2024). "His and ApoA2 presented a higher AUC than that of the best tumor biomarker CEA, with AUC of 0.724, sensitivity of 59%, and specificity of 74%." (PMID 37475010, 2023). "APOA1 and APOA2 were observed to be associated with E1A binding protein p300 (EP300) and CREB binding protein (CREBBP) which play an important role in tumor metastasis." (PMID 36428687, 2022). "In univariate analysis, clinical characteristics (gender, age, T, N, M and tumor stage), APOA2, COX6A2, HIST1H1E, UBE2C, ERO1B and eight gene comprehensive risk scores were prognostic risk factors for patients with the EC (P < 0.05)." (PMID 35568702, 2022). "While evaluating the discriminative ability, it was found that models, jointly considering information about both tumor antigens (e.g., CEA) and metabolic or inflammatory markers (e.g., ApoA2) demonstrated the highest diagnostic potential." (PMID 32528895, 2020). "In contrast, the Western blot analysis of Apoa2 relative expression has revealed an increase in its relative abundance in tumor tissues obtained from all treated groups of animals when compared to control group." (PMID 32973493, 2020). "Further lasso regression analysis identified seven potential prognostic markers (IL27, CD1D, NCOA6, CTSE, FCGRT, CFHR1, and APOA2) of robustness, most of which are related to tumor development." (PMID 32518711, 2020). "Notably, HCC with high expression of APOA2 relied on TGF-β to promote cell proliferation and angiogenesis, and pharmacological loss of TGF-β function can reduce angiogenesis and malignant tumor proliferation." (PMID 41760604, 2026). "Finally, the MMP8+ and APOA2+ TANs expressed lower levels of PD-L1, correlated with a better prognosis and were therefore predicted to play an anti-tumour role in HCC." (PMID 37534829, 2023). "ApoA2 and Cit showed better performance than the best tumor biomarker NSE for diagnosis." (PMID 37475010, 2023). "The 1q21 amplicon, as represented by YAC 789f2, was present in all tumours with 1q21-q23 amplification analysed here (and unpublished results), and it was generally present at higher copy numbers than the amplicon near APOA2 in 1q23." (PMID 16274472, 2005). "However, high SAMD4B expression could increase the instability of APOA2 mRNA, further reducing PD-L1, and thus weakening the immune escape of tumour cells from naive CD29+CD8+ T cells." (PMID 38886351, 2024).
tumor (continued). "We simultaneously ectopically expressed Myc-tagged SAMD4B, Flag-tagged APOA2 and HA-tagged immune checkpoints that are mainly expressed in tumours (PD-L1, PD-L2, FGL1 or HMGB1) and demonstrated that overexpression of SAMD4B could reduce the protein level of APOA2." (PMID 38886351, 2024). "In accordance with the results of mass spectrometric profiling of tumor tissues, these proteins were shown to be mostly increased in comparison with control, while reaching statistical significance in certain instances (AP + AG and 5-FU vs. Control for APOA2; 5-FU vs. Control for ACOT7)." (PMID 39494346, 2024). "In tumor samples taken from the GSE45001 and GSE32879 datasets, seven genes (APOA2, CAT, ACOX1, APOE4, AGXT, EHHADH, and HSD17B4) showed a substantial downregulation." (PMID 38274331, 2024). "Among the relevant immune checkpoints, especially those expressed in tumours, only PD-L1 was affected by SAMD4B and APOA2, and its expression was positively correlated with that of APOA2." (PMID 38886351, 2024). "The S100A12+, ISG15+ and TXNIP+ subtypes are found in peripheral blood, the ELL2+ and PTGS2+ mainly in adjacent liver and the MMP8+, APOA2+, CD74+, IFIT1+, SPP1+ and CCL4+ predominantly located in the tumour." (PMID 37534829, 2023). "The six HCC TAN clusters; MMP8+, APOA2+, CD74+, IFIT1+, SPP1+ and CCL4+ can be characterised by predicted function and role in tumour development." (PMID 37534829, 2023). "In liver tumors, scRNA-seq analysis identified three pro-tumor TAN subsets (CCL4+ TANs, IFIT1+ TANs, and SPP1+ TANs) and one anti-tumor subset (APOA2+ TANs)." (PMID 38066642, 2023). "The 1q23 amplicon was first observed in one single tumour (LS21), where a probe for the apolipoprotein A-II (APOA2) gene detected high amplification levels." (PMID 16274472, 2005). "In contrast, high APOA2 expression in HCC may sustain or promote PD-L1 expression, thereby enhancing tumor immune evasion." (PMID 40474968, 2025). "In addition, patients with high APOA2 and low SAMD4B expression levels had larger tumours and higher AFP levels." (PMID 38886351, 2024). "However, in the GSE32879 dataset, only seven genes (APOA2, CAT, ACOX1, APOE4, AGXT, EHHADH, HSD17B4) were observed to be significantly reduced in tumor samples." (PMID 38274331, 2024). "Adding classic tumor biomarkers (CA19-9, CEA, CYFRA21-1), then the final model consisted of 9 variables (ApoA2, Lp(a), C3, Fg, Cit, GDCA, TCDCA, CYFRA21-1, NSE), and the AUC increased to 0.871 (95%CI: 0.814 ~ 0.918) with accuracy of 81.82%, sensitivity of 77%, and specificity of 86%." (PMID 37475010, 2023). "Additionally, among downregulated hub genes, the expression of acyl-CoA oxidase 1 (ACOX1), apolipoprotein A2 (APOA2), apolipoprotein B (APOB), fibrinogen alpha chain (FGA), and fibrinogen gamma chain (FGG) were negatively correlated with the tumor stage of CCA patients." (PMID 35326644, 2022). "Furthermore, DC_c1 cells might have functional alteration and enhanced lipid utilization due to the remodeling of TME as the increased expression of CXCL9, IDO2, APOA2, and APOE compared to their non-tumor counterparts." (PMID 33298893, 2020).
cancer (30 papers, 2010 to 2026). A tumor composed of atypical neoplastic, often pleomorphic cells that invade other tissues. "Similarly, APOA2 was even better at detecting early-stage PC and identifying patients at high risk of pancreatic malignancy." (PMID 39767746, 2024). "Here, we show that apolipoprotein A2 (APOA2) mediates endothelial-to-mesenchymal transition and reprograms cancer lipid metabolism, inducing AAD resistance in HCC." (PMID 41760604, 2026). "This analysis identified several hub genes, including APOH, APOB, APOA1, and APOA2, which play significant roles in cancer progression." (PMID 39399493, 2024). "The same trend was detected for apolipoprotein C-III (APOC3), while apolipoprotein E (APOE) and apolipoprotein A-II (APOA2) were more abundant in cancer coronas for L2 and less abundant for L1 and L3, respectively." (PMID 36142503, 2022). "Furthermore, inhibition of TGF-β eliminated APOA2-mediated EndoMT and cancer lipid metabolism reprogramming." (PMID 41760604, 2026). "However, APOA2 was significantly expressed at low levels in adjacent tissues, and only patients with low APOA2 expression in cancer tissues had a better prognosis." (PMID 38886351, 2024). "However, the possible oncogenic role of modified or intact form of APOA2 is still unclear, since its expression level is frequently controversial in different cancer types." (PMID 34588485, 2021). "A comprehensive cancer detection tool employing established biomarkers (ApoA1, CA125, CA19-9, CEA, ApoA2, and TTR) has demonstrated promise in predicting multiple cancers at a reasonable cost." (PMID 38540782, 2024). "Given our current understanding of neutrophil heterogeneity across multiple cancers, therapies that expand intratumoural MMP8+ and APOA2+ TANs whilst supressing IFIT1+, SPP1+ and CCL4+ TANs may be effective in improving immunotherapy responses in HCC." (PMID 37534829, 2023).